XIAP (X-linked inhibitor of apoptosis)
Diseases named in the same sentence as XIAP in open-access papers (continued):
Sharing a sentence is not in itself a finding about the gene and the disease.
cancer (continued). "In a recent study in which XIAP was stably over-expressed at levels 2–5 times higher than normal, which is similar to levels seen in cancer samples, XIAP only provided chemoresistance when combined with the loss of the XIAP antagonist, Smac/DIABLO." (PMID 25328816, 2013). "Mammalian homologous of IAPs, including cIAP1, cIAP2, XIAP and survivin have been associated to tumor development and cancer resistant to treatment in a wide range of human cancers." (PMID 24213315, 2012). "In the current study, we further elucidated the molecular mechanisms underlying XIAP-RhoGDI protein interaction and provided the structural basis of XIAP for the contribution to mediation of cancer cell motility." (PMID 22532870, 2012). "XIAP is widely expressed in normal tissues; however, its overexpression in cancer is usually associated with an unfavorable prognosis." (PMID 23259070, 2012). "Increased expression of XIAP is found in many cancer tissues and associated with chemoresistance, disease progression and poor prognosis." (PMID 22532870, 2012). "Although an increased expression level of XIAP is associated with cancer cell metastasis, the underlying molecular mechanisms remain largely unexplored." (PMID 22532870, 2012). "Based on our in vitro observations, we expected that FL118 should effectively inhibit tumor growth in vivo, since FL118 inhibited multiple cancer survival-associated genes (survivin, Mcl-1, XIAP and cIAP2)." (PMID 23029106, 2012). "IAPs such as XIAP are highly expressed in various cancers and are associated with poor prognosis and resistance to apoptosis." (PMID 22218530, 2012). "Most human cancers have high levels of IAPs, including the X-linked inhibitor of apoptosis protein (XIAP) isoform, which are associated with poor treatment responses." (PMID 20981352, 2011). "X-linked inhibitor of apoptosis protein (XIAP) is often overexpressed in cancer cells, where it plays a key role in survival and also promotes invasiveness." (PMID 20712893, 2010). "XIAP has been shown in other cancers to be associated with resistance to chemotherapy, as well as resistance to radiation therapy." (PMID 17257402, 2007). "Mechanistically, this functional role may be linked to the activation of the XIAP‐Bcl‐xl pathway, consistent with our analysis of other cancer types." (PMID 40959971, 2025). "One such example is XIAP (X-linked inhibitor of apoptosis protein), an E3 ubiquitin ligase that has been shown to promote resistance to therapy-induced apoptosis and confer poor outcome in cancer patients." (PMID 41323787, 2025). "A gene array, real-time PCR, and Western blotting of SMAD7 AS-treated cells showed a marked down-regulation of the X-linked inhibitor of apoptosis protein (XIAP), a member of the inhibitor of apoptosis family, which has been implicated in cancer cell migration." (PMID 39001432, 2024). "Also, TRIM8 stabilizes the X-linked inhibitor of apoptosis (XIAP), a molecule modulating cell death and autophagy, thereby promoting the survival of cancer cells." (PMID 39224802, 2024). "Therefore, in accordance with our data, cancer cells expressing the V225I mutant, or another mutation in the caspase-cleavage site of HuR, would have increased XIAP expression and thus have an increased likelihood of resistance to cancer therapy." (PMID 39695179, 2024). "Mounting evidence demonstrates that XIAP promotes the growth, invasion, and metastasis of malignant cells, confers resistance to certain chemotherapeutic drugs, and associates with poor outcome in a variety of cancers." (PMID 37154878, 2023).
cancer (continued). "Inhibition of apoptosis by the X-linked inhibitor of apoptosis protein (XIAP) is one of the leading causes of tumor cells growth and the high expression of XIAP is frequently one culprit in different types of cancer and plays an important role in developing chemoresistance." (PMID 36615253, 2022). "Notably, the anti-apoptotic XIAP, which is a biomarker of cancers and causes apoptosis resistance to some cancer therapies, was decreased by C6 treatment in HCT116 cells." (PMID 35408786, 2022). "The X-linked inhibitor of apoptosis protein is abnormally expressed in a variety of human cancers." (PMID 36142793, 2022). "In addition to regulating mTOR and iNOS pathways, sestrin 2 has been shown to promote cancer cell apoptosis by targeting X-linked inhibitor of apoptosis protein (XIAP) and suppress cell migration and invasion by targeting hypoxia inducible factor-1α (HIF-1α)." (PMID 34784907, 2021). "Furthermore, the antiapoptotic genes BCL2 and XIAP (X-linked inhibitor of apoptosis) are downregulated by natural products and upregulated in several cancer tissues." (PMID 34422220, 2021). "X-linked inhibitor of apoptosis (XIAP) suppresses apoptosis in cancer cells." (PMID 32537434, 2020). "concentrate and cordycepin elicit apoptosis via caspase-7, -8, and -9 involving the increase of Bcl-2-associated x protein (Bax)/Bcl-2 protein expression ratio and decreasing X-linked inhibitor of apoptosis protein (XIAP) thus confirming its anti-cancer property." (PMID 33628175, 2020). "Thus, it is possible that the degradation of XIAP by HtrA4, in order to promote apoptosis, needs other pro-apoptotic events to occur in parallel, especially in the cancer cells that usually have mutations inhibiting apoptosis." (PMID 31546993, 2019). "Interestingly, in silico screening predicts that embelin inhibits the X-linked inhibitor of apoptosis protein (XIAP), which is over-expressed in a variety of cancers, especially drug-resistant ones." (PMID 31379579, 2019). "Thus, we checked the expression of X-linked inhibitor of apoptosis protein (XIAP), a member of the family of anti-apoptotic proteins, whose overexpression in cancer cells is associated to resistance to a variety of apoptotic stimuli." (PMID 31799185, 2019). "X-linked inhibitor of apoptosis protein (XIAP) is an emerging crucial therapeutic target in cancer." (PMID 31505859, 2019). "Inhibitor of apoptosis (IAP) proteins that include cIAP1 (cellular inhibitor of apoptosis protein-1), cIAP2, XIAP (X-linked inhibitor of apoptosis protein), and survivin promote survival of cancer cells by inhibiting apoptosis and have been proposed to be therapeutic targets in cancer." (PMID 30049957, 2018). "Activated AKT has been found to be functionally associated with XIAP expression in many cancers." (PMID 28704451, 2017). "We further revealed that inhibition of CD147 and subsequent XIAP depletion might have an anti-tumor effect through enhancing the susceptibility of cancer cells to 5-fluorouracil-induced apoptosis." (PMID 28445958, 2017). "These included genes involved in cell death and survival processes (BCLAF1, CFLAR, CASP1, and XIAP), genes associated with proliferation-driving transcription or cancer (KLF4, LEF1, SOX4, ID3), and genes associated with inflammation (CD28, CCR7, CX3CR1 and IFNG)." (PMID 28407008, 2017). "Recently we and other have shown a functional association of AKT and XIAP in cancer cells." (PMID 28704451, 2017). "Altered expression of XIAP has been shown in different kinds of human pathogenesis; loss of XIAP was reported to increase the sensitivity of cells to death, while upregulation of XIAP is revealed in many human cancers and associated with chemical or radiation resistance." (PMID 28186968, 2017).
cancer (continued). "In addition, we found that CD133+ MB cells with features of cancer stem cells displayed higher levels of X-linked inhibitor of apoptosis (XIAP) and cellular inhibitor of apoptosis 1/2 (cIAP1/2), and were hypersensitive to treatment with IAP inhibitors." (PMID 27537345, 2016). "Therefore, we appreciate that the definitive causal contributions of the XIAP/cIAP1-Beclin 1-autophagy pathway to cancer still will require further studies." (PMID 25669656, 2015). "A biochemical examination of PL-induced cell death indicated that it represses various anti-apoptotic proteins including B-cell CLL/lymphoma 2 (BCL2), baculoviral IAP repeat-containing 5 (also known as survivin) and X-linked inhibitor of apoptosis (XIAP) in cancer cells." (PMID 25984950, 2015). "In addition to observations derived from functional studies, the fact that XIAP expression positively associates with a favorable prognosis in some cancers has led to question the pro-tumor role of this IAP." (PMID 26507126, 2015). "Our finding of the effect of XIAPΔRING on cancer cell growth and cytokinesis suggests that nuclear XIAP might contribute to genetic instability associated with cell cycle and checkpoint perturbation." (PMID 25216527, 2014). "Patients that belong to subgroups where high cancer cell specific XIAP expression causes poor cancer therapy response may have a therapeutic benefit if they are treated with XIAP-targeting drugs that specifically neutralize the protective effect of XIAP." (PMID 25120954, 2014). "Another IAP-denominated XIAP (X-linked inhibitor of apoptosis protein), in contrast to survivin, is widely expressed in normal tissues but, similar to survivin, XIAP overexpression in cancer is usually associated with an unfavourable prognosis." (PMID 24070327, 2013). "Consistent with its antitumor activity potential, FL118 selectively inhibits multiple cancer survival-associated genes (survivin, Mcl-1, XIAP and cIAP2), while inducing proapoptotic factors Bax and Bim, and showing no inhibitory effects on control genes (p21, DHFR, HTR and TK)." (PMID 23029106, 2012). "Interestingly, while some studies demonstrate that high levels of XIAP have an unfavorable prognosis in cancers of various tissue origins, other data suggest that elevated XIAP levels are associated with a favorable clinical outcome." (PMID 20618956, 2010). "The X-linked Inhibitor of Apoptosis (XIAP) has attracted much attention as a cancer drug target." (PMID 20067634, 2010). "However, the mechanism by which FL118 regulates multiple cancer‐associated proteins (survivin, Mcl‐1, XIAP and cIAP2) is unknown and requires further study." (PMID 35604033, 2022). "Further, inhibition of XIAP expression increased cell migration, suggesting that although cancer cell invasion and migration are appealingly linked in many experimental systems, they may be divergent in their significance to and mechanism in human BC cells, as shown in our recently studies." (PMID 31811115, 2019). "X-linked inhibitor of apoptosis protein (XIAP), cellular inhibitors of apoptosis 1 and 2 (cIAP 1 and cIAP 2) belong to the inhibitor of apoptosis proteins (IAPs), which represent a family of endogenous caspase inhibitors and also play an important role in inducing apoptosis of cancer cells." (PMID 30400387, 2018). "Therefore, as an important diagnostic and prognostic biomarker in many cancers, XIAP may serve as a potential therapeutic target for antineoplastic therapy." (PMID 28057023, 2017). "At least five alternative splice variants of survivin have been reported that also conserve the XIAP and Smac/Diablo protein binding regions but have distinct levels of association with chemoresistance and other important clinico-pathological features in cancer." (PMID 27613060, 2016).
cancer (continued). "Since autophagy promotes cancer cell survival at late stages of the disease, the Beclin 1-dependent autophagy activation may contribute to the chemotherapy resistance associated with XIAP and cIAP1 overexpression found in several types of human cancer." (PMID 25669656, 2015). "Thus, the chemotherapy resistance associated with XIAP and cIAP1 overexpression observed in several human cancers may be, at least in part, due to the Beclin 1-dependent autophagy activation by IAPs described in this study." (PMID 25669656, 2015). "X-linked inhibitor of apoptosis protein (XIAP) is constitutively expressed endogenous inhibitor of apoptosis, exhibit its antiapoptotic effect by inactivating key caspases such as caspase-3, caspase-7 and caspase-9 and also play pivotal role in rendering cancer chemoresistance." (PMID 23613836, 2013). "The X-linked inhibitor of apoptosis protein (XIAP) is a key suppressor of apoptosis, crucial for cellular differentiation, embryogenesis, and cancer progression." (PMID 41842907, 2026). "Among the upregulated genes were those linked to cancer formation (e.g., STOX1, PEG3, XIAP) and immune cell recruitment (e.g., CCL28, VIM), suggesting a shift towards increased cellular proliferation and remodelling of the immune microenvironment." (PMID 40683913, 2025). "The expression of both Ki-67 and XIAP was significantly increased in the IMWA-treated cancer tissues of C57BL/6 mice and NTG mice." (PMID 39917292, 2025). "We demonstrated by selectively alkylating caspase 7 (CASP7) to release the active CASP7 for killing the drug-resistant cancer cells with accumulated XIAP:CASP7 resulted from caspase-3 down-regulation (CASP3/DR)." (PMID 40533441, 2025). "The results showed that the XIAP inhibitor AZD5582 regulated the tumor immune microenvironment of cancer tissues in C57BL/6 mice." (PMID 39917292, 2025). "Our studies not only serve as a proof-of-concept for using XIAP:CASP7 as a drug target, but also provide the first reversible XIAP:CASP7 inhibitor for cancer therapy of CASP3/DR malignancies." (PMID 40533441, 2025). "Because CASP3/DR combined with XIAP:CASP7 accumulation correlates with the aggressive evolution of clinical malignancies and a poor prognosis in cancer patients, targeting XIAP:CASP7 represents an effective treatment against these malignant cancers." (PMID 40533441, 2025). "IMT of XIAP mRNA contributes to cell survival under stress and cancer progression by ensuring continuous production of the protein, thus promoting resistance to apoptosis." (PMID 40940829, 2025). "This newly understood mechanism positions ARTS and its interaction with XIAP and Bcl-2 as promising targets in the development of next-generation therapies for cancers resistant to conventional treatments." (PMID 40841912, 2025). "XIAP is the most extensively studied member of IAPs in apoptosis and in cancer, and it can exert its function through direct and indirect mechanisms." (PMID 40223934, 2025). "The Hepa1-6 cell-derived subcutaneous xenograft of C57/BL6 mice were treated with insufficient MWA to evaluate the XIAP expression in the residual cancer tissue." (PMID 39917292, 2025). "XIAP is also closely related to the progression and aggression of malignant tumors and contributes to chemotherapy resistance." (PMID 41253834, 2025). "By directly inhibiting caspases and blocking apoptosis, XIAP allows cancer cells to evade cell death mechanisms triggered by these drugs, leading to treatment failure and disease progression." (PMID 40223934, 2025). "XIAP is a well-studied apoptosis inhibitor that directly inhibits caspase-3 activation, and it is widely known that overexpression of XIAP renders cancer cells resistant to apoptosis." (PMID 40544190, 2025).
cancer (continued). "Dysregulation of cyclins and cyclin-dependent kinases (CDKs) is a hallmark of cancer progression, and inhibition of CDK2 has been shown to suppress XIAP (X-linked inhibitor of apoptosis protein), thereby promoting caspase-mediated apoptosis." (PMID 41323392, 2025). "Ceramide and its analog LCL85 are potent sensitizers of Fas-mediated apoptosis and inhibit cancer progression by effectively targeting the protein degradation of cIAP1 and XIAP." (PMID 38521878, 2024). "It has been proven that inhibiting or completely silencing the expression of the XIAP gene leads to an increased sensitivity of cells to cisplatin and promotes apoptosis in cancer cells." (PMID 39769428, 2024). "Based on the understanding the core mechanism of XIAP, drug development strategy has been mainly focused on anti-cancer effect by suppressing the activity of XIAP and their related partners." (PMID 38191507, 2024). "Post‐transcriptional upregulation of XIAP by various mechanisms in conjunction with limited therapy response has been reported for multiple cancer entities." (PMID 36416169, 2023). "XIAP is ubiquitously expressed in human normal tissues (Human Protein Atlas proteinatlas.org) and overexpressed in many cancer cell lines and cancerous tissues." (PMID 36845731, 2023). "XIAP has been reported to be highly expressed in a variety of malignant tumours and closely related to their occurrence, development and prognosis." (PMID 37154878, 2023). "Xevinapant is a potent, oral, small-molecule IAP inhibitor that blocks XIAP and cIAP1/2, restoring cancer cell sensitivity to apoptosis and, thereby, is thought to enhance the effects of anticancer treatments such as chemotherapy and radiotherapy." (PMID 36640618, 2023). "Smac/DIABLO mimetics proved to be effective in overcoming cancer-acquired resistance to apoptosis as a consequence of overexpression of the anti-apoptotic proteins XIAP, cIAP1, and cIAP2." (PMID 37711175, 2023). "DDX5 is an upstream master regulator in cancer and positively controls the expression of survivin, Mcl-1, XIAP, and cIAP2." (PMID 36771042, 2023). "Previous studies have revealed that the increased expression of XIAP and Survivin activates the metastasis and chemoresistance of cancer." (PMID 38137377, 2023). "SMAC mimetics basically contain the AVPI motif of SMAC to inhibit cIAP1, cIAP2 and XIAP or to induce their auto-ubiquitination for subsequent proteasomal degradation, which lowers the threshold for apoptosis in cancer cells." (PMID 36845731, 2023). "Regarding the underlying mechanism, melatonin negatively regulated the resistance of cancer cells to apoptosis through targeting of oxidative stress, X-linked IAP (XIAP) and survivin in CRC cells, hence decreasing the cell proliferation." (PMID 36759799, 2023). "In terms of biochemical mechanisms, NF-κB activation by the engagement of TLRs plays a pivotal role in cancer proliferation, survival, angiogenesis, and progression through the up-regulation of IL-6, Bcl-xL, Bcl-2, Bcl-xs, XIAP, and VEGF genes." (PMID 37287005, 2023).